C7orf33 (chromosome 7 open reading frame 33)
Tractability: No criterion of Open Targets' tractability assessment is met for any kind of drug.
Gene: Protein-coding gene on chromosome 7 (148,590,766 to 148,615,860, forward strand). Ensembl gene ENSG00000170279.
Subcellular location (Human Protein Atlas): Acrosome; Equatorial segment
Genetic constraint (gnomAD): Loss-of-function variants: 15 observed, 13.47 expected, observed/expected ratio (o/e) 1.11, 90% interval 0.74 to 1.68. The upper end of that interval is the gene's LOEUF score, 1.68, which puts it in group 6 of 6, group 1 being the genes least tolerant of losing a copy. Missense variants: 177 observed, 225.3 expected, observed/expected ratio (o/e) 0.79, 90% interval 0.69 to 0.89. Synonymous variants: 73 observed, 87.15 expected, observed/expected ratio (o/e) 0.84, 90% interval 0.69 to 1.02.
Homologues: Orthologues: chimpanzee C7H7orf33 (98% identical), macaque C3H7orf33 (91% identical).